EGFR (epidermal growth factor receptor)
Diseases named in the same sentence as EGFR in open-access papers (continued):
Sharing a sentence is not in itself a finding about the gene and the disease.
cancer (continued). "As in many other cancers, EGFR plays a prominent role in promoting growth of CRC; biological therapies targeting EGFR are FDA-approved for treatment of EGFR-positive advanced CRC." (PMID 23119029, 2012). "Molecular cancer therapies targeting EGFR and HER2 have been successfully applied in the clinic for treatment of different cancers." (PMID 23342251, 2012). "A recombinant antibody, cetuximab, is approved for the clinical treatment of cancers that overexpress wild-type EGFR." (PMID 24213504, 2012). "Dysregulation and a resulting prominent pathophysiological role of the epidermal growth factor receptor (EGFR) have been identified in several different malignant tumor entities, GBM among them." (PMID 24213322, 2012). "By expressing a chimera of the C. elegans and human EGFR proteins in C. elegans, we have developed and characterized an animal model system that can be used to screen EGFR inhibitor anti-cancer drugs." (PMID 22957020, 2012). "EGFR exons 18, 19, 20 and 21 of both cancer cell and white blood cell were finally successfully sequenced." (PMID 22252115, 2012). "The level of EGFR protein expression was determined for a panel of six human GC cancer cell lines, and mRNA status was assessed by real-time PCR." (PMID 22139134, 2012). "In the examples reported herein, the absorption of EGFr inhibitors was considered for cancer cells alone." (PMID 22713695, 2012). "EGFR/PI-3Kinase enhances lipogenesis in cancer cells by activating lipogenic fatty acid synthase (FASN) machinery in conjunction with PPAR γ." (PMID 22509304, 2012). "The epidermal growth factor receptor (EGFR) is involved in many cancers and EGFR has been heavily pursued as a drug target." (PMID 23166750, 2012). "Gefitinib is an orally active selective inhibitor of the epidermal growth factor receptor (EGFR) tyrosine kinase, an enzyme that regulates the intracellular signaling pathways implicated in the proliferation and survival of cancer cells." (PMID 22405425, 2012). "In contrast, the EGFR signaling upregulation has been involved in cancer development in many tissues." (PMID 23050157, 2012). "Small molecule therapeutics and recombinant antibodies are being developed as potential treatments for cancers driven by increased activity of EGFR, FGFR and/or PI3K/AKT." (PMID 24213504, 2012). "The important role of the EGFR signaling pathway in oncogenesis made it a good candidate for targeted cancer therapy." (PMID 23233863, 2012). "In recent years inhibitors directed against the epidermal growth factor receptor (EGFR) have evolved as effective targeting cancer drugs." (PMID 22472354, 2012). "The correlation between over-expression of EGFr and clinically aggressive malignant disease suggested that EGFr was a promising target for several epithelial tumours, which represent approximately two thirds of all human cancers." (PMID 22713695, 2012). "Several studies have demonstrated that microRNA-7 (miR-7) regulates EGFR expression and Akt activity in a range of cancer cell types via its specific interaction with the EGFR mRNA 3′-untranslated region (3′-UTR)." (PMID 23115635, 2012). "Models of bone metastasis have provided evidence that cancer cell activation of EGFR often leads to the production of paracrine signaling molecules necessary for survival and rapid growth within the bone." (PMID 22276166, 2012). "NCT00848718 is a clinical trial with patients having advanced cancers to examine the effects of combining MK-2206 and the EGFR inhibitor erlotinib, docetaxel, or carboplatin + paclitaxel." (PMID 23085539, 2012). "We assayed peptides from the JXM region for anti-cancer properties and for their ability to modulate EGFR signaling." (PMID 23166750, 2012). "Nowadays, EGFR status is a prognostic tool in several cancers, indicating poor survival, more aggressive behavior, increased risk of invasion/metastasis, and resistance to antineoplastic therapies." (PMID 23233863, 2012).
cancer (continued). "MNT can be utilized to deliver 125I into the nuclei of cancer cells overexpressing EGFR, significantly enhancing cytotoxicity." (PMID 23107475, 2012). "EGFR overexpression activates PPAR-gamma function in cancer cells to protect them from palmitate toxicity." (PMID 22509304, 2012). "Here, we investigated the correlation of serum levels of panitumumab, receptor occupancy of the EGFR, and inhibition of EGFR signaling with inhibition of cellular proliferation with antitumor activity in mouse model of human cancer." (PMID 22830443, 2012). "Hence, we hypothesized that peptides encoding the EGFR JXM region could have anti-cancer activity." (PMID 23166750, 2012). "High levels of EGFR are correlated with poor prognosis and resistance to radiation therapy in a variety of cancers including SCCHN." (PMID 22778735, 2012). "In particular, the detection of functional responses of cells to EGFR signaling has attracted tremendous interests due to the biological significance of EGFR in cancer diagnosis, treatment, and prognosis." (PMID 25586035, 2012). "Recently, the important role of HER3 as an obligate partner for HER receptor dimerization and in primary and acquired resistance to HER2- or EGFR-targeted therapy has brought considerable attention to HER3 from cancer researchers." (PMID 23198146, 2012). "EGFR and EGFR ligands have been extensively studied because the inactivation of EGFR represents a promising strategy for the treatment of several cancers." (PMID 22646534, 2012). "We focused on the EGFR pathway because it plays an important role in epithelial cell regulation and cancer biology, and there is mounting evidence that EGFR transactivation is coupled to wide variety of external stimuli." (PMID 22479638, 2012). "Two thirds of these novel targeted anticancer agents inhibit kinases, including EGFR, Src, and mammalian target of rapamycin (mTOR) activated in cancer cells as well as in microenvironment cells and now several V-ATPases inhibitors are under trial." (PMID 22949815, 2012). "Taken together these observations indicate that TE-64562 can function as a selective anti-cancer drug for tumors that are EGFR positive." (PMID 23166750, 2012). "Because survival of cells with genetic mutations is essential for cancer initiation and Akt and ERK are well known survival signals, we next investigated if BPDE-induced and EGFR-mediated Akt and ERK activation protects cells from BPDE-induced cytotoxicity." (PMID 22457794, 2012). "EGFR and KRAS are part of the same signaling pathway, and EGFR overexpression as well as activating KRAS mutations contribute to development and progression of several human cancers, including CRC." (PMID 23173730, 2012). "While most new approvals of drugs for target cancer therapies are directed against a few existing targets, such as EGFR, ABL1, only a small number of compounds are in development against novel targets." (PMID 22952662, 2012). "The anti-EGFR therapies have displayed promising activity in the clinic in certain cancer types; however, there are issues with intrinsic and acquired resistance." (PMID 23166750, 2012). "From these results, we conclude that TE-64562 displayed relative selectivity of activity in cancer cell lines where EGFR is expressed and contributes to proliferation and survival." (PMID 23166750, 2012). "More surprisingly, 26 of the 29 known Hsp90 client kinases that we also quantified in the reference Hs68 cell line showed significantly reduced levels after 24 h of treatment, including well known cancer-relevant proteins like EGFR, Met and PDGFRα/β." (PMID 22277058, 2012). "Overexpression of EGFR has been observed and its prognostic significance confirmed in various cancers." (PMID 22784503, 2012).
cancer (continued). "Our findings, taken together with these observations, suggest the possibility that aberrant activation of EGFR in cancer can lead to acquisition and maintenance of stem cell properties." (PMID 22384257, 2012). "In exon 20, a variant from CAG to CAA at codon 787 (2361G-> A) was identified in 19 patients, which was a genomic variation of EGFR since it was found in both cancer tissue and white blood cells." (PMID 22252115, 2012). "Others are antibodies such as Trastuzumab, acting against human epidermal growth factor receptor 2 (HER-2) on cancer cells, or Cetuximab, that acts against the epidermal growth factor receptor (EGFR)." (PMID 23087898, 2012). "As EGFR is known to promote proliferation of cancer cells, dual targeting of VEGF with bevacizumab and EGFR with erlotinib was considered to be a logical treatment approach for advanced HCC." (PMID 23284624, 2012). "EGFR specific tyrosine kinases inhibitors like gefitinib and erlotinib received regulatory approval for use in cancer patients." (PMID 22291909, 2012). "Deregulation of the EGFR signaling pathway is one of the most frequently observed genetic abnormalities that drives cancer development." (PMID 22994622, 2012). "Previously, we and others identified the EGFR mRNA 3′-UTR as a specific target of miR-7 in multiple different cancer cell lines, and demonstrated that miR-7 is a potent inhibitor of EGFR signaling and cell viability." (PMID 23115635, 2012). "In both cancer and wound healing, targeting EGFR endocytic trafficking is a viable pharmacological strategy." (PMID 23344022, 2012). "Activation of EGFR also resulted in increased tumorsphere formation, a characteristic ability of cancer stem cells." (PMID 22384257, 2012). "We therefore conclude that our modeling results with respect to the impact of miRNAs on the EGFR pathway are in good accordance with published data of some of the miRNAs that are relevant in cancer treatment." (PMID 22253908, 2012). "Understanding the mechanisms that regulate EGFR signaling will aid in developing therapeutic compounds for the treatment of various maladies, such as cancer and wound healing." (PMID 23344022, 2012). "PI3K/Akt signalling is one of the most critical cancer-promoting pathways through upregulation of growth factor receptors (EGFR, IGF1R, HER2, etc) or PTEN inactivation and recently considered a major determinant of trastuzumab resistance." (PMID 22454081, 2012). "These include the cytoplasmic protein vimentin, and three different cell surface proteins; EGFR, N-cadherin, and the reported cancer stem cell maker, CD44." (PMID 22844540, 2012). "EGFR also appears to protect cancer cells from toxic actions of chemotherapy and radiotherapy, rendering these treatment modalities less effective." (PMID 22253908, 2012). "Specific inhibition of EGF receptors (EGFR) abolishes cytoskeleton remodeling and migration of cancer cells in response to EGF." (PMID 22701712, 2012). "Cytotoxicity against NCI-H1975 cancer cell line and EGFR inhibitory activity of Gefitinib and its analogues." (PMID 23185274, 2012). "In recent years, a variety of newly developed targeted anti-cancer therapies have successfully been combined with classic therapies, including the combination of EGFR-inhibition and radiotherapy in HNSCC." (PMID 23046567, 2012). "Constitutive activation of EGFR has been reported in various cancers including breast, prostate and ovarian." (PMID 22952709, 2012). "ERβ1 induces the expression of E-cadherin by down-regulating EGFR, an oncogenic factor that is expressed in basal-like cancers." (PMID 23158001, 2012). "Overexpression of EGFR promotes migration and invasion of basal cells and its expression correlates with poor survival in basal-like cancers." (PMID 23158001, 2012). "The epidermal growth factor receptor (EGFR) is recognized as an important molecular target in cancer therapy." (PMID 23008811, 2012).
cancer (continued). "Progress in the understanding of cancer biology have driven the development of drugs against specific molecular targets, such as epidermal growth factor receptor (EGFR) and vascular endothelial growth factor (VEGF) and its receptors (VEGFRs)." (PMID 23077602, 2012). "A relevant study has previously demonstrated that HER2/HER3-driven signaling pathway limits sensitivity to EGFR targeted drugs in cancer cells." (PMID 22815900, 2012). "EGFR signaling is not only critical for cell proliferation, but also to processes that are crucial for cancer progression, including angiogenesis, metastasis, and inhibition of apoptosis." (PMID 26316937, 2012). "Biological activities of Y-142 were assessed in cancer cell proliferation and angiogenesis assays and compared with the anti-EGFR antibody cetuximab, the HB-EGF inhibitor CRM197, and the anti-vascular endothelial growth factor (VEGF) antibody bevacizumab." (PMID 23251664, 2012). "Here we have shown that EGFR possibly fulfills that role, as EGFR activation promoted the acquisition and maintenance of various cancer stem cell characteristics including the expression of self-renewal markers and capacity to form tumorspheres." (PMID 22384257, 2012). "Taken together, these results indicate that the juxtamembrane domain of EGFR is a viable drug target for several cancers." (PMID 23166750, 2012). "Nuclear EGFR has been shown to contribute to resistance to various cancer therapies, such as radiation, cisplatin, and cetuximab." (PMID 22520625, 2012). "EGFRvIII is a cancer-specific deletion of exons 2 to 7 (801 bp) that results in a truncated extracellular domain of EGFR." (PMID 22359620, 2012). "The specific inhibition of the EGFR TK by small molecules, such as imatinib for chronic myelogeneous leukemia, started the targeted therapy era in cancer treatment." (PMID 23691449, 2012). "An anti-EGFR monoclonal antibody inhibits EGFR activation, resulting in the enhancement of the anti-cancer effect of cisplatin." (PMID 22788833, 2012). "Previous studies have indicated that GPER activation triggers the EGFR-dependent signaling in cancer cells, even involving a functional cross-talk between these receptors." (PMID 22251451, 2012). "Elevated levels of the EGFR has been identified as a common component of multiple cancer types and appear to promote solid tumor growth." (PMID 23194200, 2012). "EGFR is a validated, potential therapeutic target in many human cancers including colorectal, ovarian, head and neck, bladder, lung, pancreatic, and breast." (PMID 22554165, 2012). "Recent studies have shown that GPR30 is expressed in a variety of estrogen-responsive cancer cells, and that it activates the epidermal growth factor receptor (EGFR) transduction pathway in various malignancies." (PMID 23163984, 2012). "Accordingly, it has been shown that the EGFR contributes to the survival of cancer cells independent from its kinase activity." (PMID 22815959, 2012). "Anti-EGFR monoclonal antibodies and direct inhibition of the EGFR tyrosine kinase activity are among the most explored anti-cancer targeted therapies." (PMID 23285165, 2012). "Among these biomarkers, amplification of EGFR has been extensively studied and is regarded as a poor prognostic factor in cancer." (PMID 23110940, 2012). "Overall, the hazard ratios of cancer progression were 4.611 (95% CI: 2.5–8.4) for EGFR and 1.067 (95% CI: 0.59–1.97) and ErbB2 overexpression." (PMID 22991510, 2012). "The epidermal growth factor receptor (EGFR) signalling pathway is frequently dysregulated in several cancer types." (PMID 22359620, 2012). "The EGFR-related pathway was also identified as a transformation-related pathway in multiple cancer types and appears to promote growth of solid tumors." (PMID 23259795, 2012).
cancer (continued). "As for EGFR we found its expression to be moderate to strong in cytoplasm of cancer cells and weak in small ductal cells." (PMID 23304126, 2012). "The rate of mPRα-HiEx was significantly higher in cancers with EGFR expression (61.54% vs. 24.56%, P=0.02); and after adjusting for age and/or TNM stage, the association remained (P=0.04)." (PMID 22496908, 2012). "In recent years inhibitors directed against the epidermal growth factor receptor (EGFR) have evolved as effective cancer-targeting drugs." (PMID 22472354, 2012). "This high percentage of EGFR expression in BLBCs is important, not only for the diagnosis of BLBCs, but also in the treatment of this high grade and TN cancers." (PMID 23082819, 2012). "Several anti-EGFR strategies that target different components of the EGFR-pathway have been developed in different cancer models." (PMID 23233863, 2012). "Cetuximab, an anti-EGFR monoclonal antibody used as a cancer therapeutic agent, suppresses EGFR-dependent cancer cell growth by inhibiting EGFR activation." (PMID 23251664, 2012). "EGFR is overexpressed in several cancers, including colon, breast and brain, and diverse drugs targeting ErbB1 have been developed." (PMID 23202898, 2012). "In the presence of androgens, endogenous and ectopically expressed AR directly associates with EGFR and decreases the activation of downstream PI3K signaling leading to cancer cell growth and survival." (PMID 23185449, 2012). "Currently, targeted chemotherapy is administered to LAD patients having a particular genomic alteration, e.g. EGFR inhibitors (erlotinib, gefitinib) for EGFR mutant cancers." (PMID 22590557, 2012). "Given the multiplicity of the resistance mechanisms to EGFR therapies, new approaches to targeting EGFR are important to cancer drug discovery." (PMID 23166750, 2012). "In particular, overexpression and amplification of the EGFR is present in the majority of TNBC as well as other cancers and portends poor prognosis, inferior survival, radioresistance, and treatment failures." (PMID 23071597, 2012). "EGFR mRNA expression increases as disease progresses from a benign to a malignant tumor, likely due to the homogeneity of the cell population." (PMID 23319880, 2012). "This is significant as crosstalk between EGFR and BDNF receptor TrkB has been shown to induce cancer cell migration and response to EGF is a key step during cancer cell invasion and is directly linked with metastasis." (PMID 23285024, 2012). "The aim of the present study was to determine the frequency of EGFR and KRAS mutations in NSCLC in the West European Dutch population in primary carcinomas and different metastatic locations." (PMID 22528563, 2012). "In this study, 16.3% of the carcinomas presented high polysomy or amplification of the EGFR gene and 19.7% showed overexpression of the EGFR protein." (PMID 22240798, 2012). "In our present study, we focused on the change in EGFR expression because miR-7 was reported to inhibit EGFR expression and subsequently suppress cell proliferation in several human carcinoma cell lines." (PMID 23227519, 2012). "Using quantitative fluorescence immunohistochemistry and AQUA® technology, we analyzed EGFR protein expression in our OSCC cohort and found that exceptionally high EGFR expression in carcinoma cells was associated with EGFRvIII positivity." (PMID 22359620, 2012). "On one hand, the simultaneous expression of a differentiated pattern and high levels of EGFr display a higher degree of accelerated repopulation compared to carcinomas with low levels of EGFr or poor differentiation." (PMID 22920680, 2012). "The level of EGFR protein expression in HNSCC can vary according to the specific subsite; for instance, carcinomas of the pharynx and oral cavity tend to have higher EGFR expression than those of the larynx." (PMID 22359620, 2012). "Here, we have identified signaling events coordinated by EGFR and integrin αvβ5 that regulate the invasive behavior of human carcinoma cells." (PMID 22586492, 2012).